ENSG00000286132 (novel protein)
Gene: Protein-coding gene on chromosome 19 (12,075,327 to 12,113,325, forward strand). Ensembl gene ENSG00000286132.
Genetic constraint (gnomAD): Missense variants: 733 observed, 730.9 expected, observed/expected ratio (o/e) 1, 90% interval 0.94 to 1.07. Synonymous variants: 234 observed, 234.31 expected, observed/expected ratio (o/e) 1, 90% interval 0.9 to 1.11.